RNU1-48P (RNA, U1 small nuclear 48, pseudogene)
Gene: Small nuclear RNA gene on chromosome Y (18,486,511 to 18,486,672, forward strand). Ensembl gene ENSG00000252209.
Homologues: Paralogues in human: RNU1-41P (100% identical), RNU1-128P (86% identical), RNU1-40P (86% identical), RNU1-95P (86% identical), RNU1-97P (86% identical), RNU1-1 (85% identical), RNU1-2 (85% identical), RNU1-27P (85% identical), RNU1-28P (85% identical), RNU1-3 (85% identical), RNU1-4 (85% identical), RNVU1-18 (85% identical), and 134 more.